COL1A1 (collagen type I alpha 1 chain)
Description:
Type I collagen is a member of group I collagen (fibrillar forming collagen).
Synonyms: OI4; CAFYD; EDSARTH1; EDSC; OI1; OI2; OI3
Tractability: Small molecule: a structure with a bound ligand is known. Antibody: its Gene Ontology location is reachable by antibodies, with high confidence; UniProt places it where antibodies can reach, with medium confidence; UniProt predicts a signal peptide or a membrane-spanning region. PROTAC: ubiquitination databases record sites on it; its protein half-life has been measured. Other modalities: an approved drug acts on it.
Target class: Structural protein
Safety:
Unwanted effects reported when the protein is acted on. In parentheses: how it was acted on, where the effect was seen, and who reports it.
bone density (source: ClinPGx)
Gene: Protein-coding gene on chromosome 17 (50,184,101 to 50,201,634, reverse strand). Ensembl gene ENSG00000108821.
Subcellular location: Secreted, extracellular space, extracellular matrix
Subcellular location (Human Protein Atlas): Endoplasmic reticulum; Vesicles; Predicted to be secreted
Pathways (Reactome):
Extracellular matrix organization: Anchoring fibril formation; Assembly of collagen fibrils and other multimeric structures; Collagen biosynthesis and modifying enzymes; Collagen chain trimerization; Collagen degradation; Crosslinking of collagen fibrils; ECM proteoglycans; Fibronectin matrix formation; Integrin cell surface interactions; Non-integrin membrane-ECM interactions; Syndecan interactions
Disease: Defective VWF binding to collagen type I; Defective VWF cleavage by ADAMTS13 variant; Defective binding of VWF variant to GPIb:IX:V; Enhanced binding of GP1BA variant to VWF multimer:collagen; Enhanced cleavage of VWF variant by ADAMTS13
Hemostasis: Cell surface interactions at the vascular wall; GP1b-IX-V activation signalling; GPVI-mediated activation cascade; Platelet Adhesion to exposed collagen; Platelet Aggregation (Plug Formation)
Developmental Biology: Developmental Lineage of Pancreatic Ductal Cells
Gene expression (Transcription): RUNX2 regulates osteoblast differentiation
Immune System: Immunoregulatory interactions between a Lymphoid and a non-Lymphoid cell
Signal Transduction: MET activates PTK2 signaling
Vesicle-mediated transport: Scavenging by Class A Receptors
Gene Ontology:
Molecular function: extracellular matrix structural constituent conferring tensile strength; identical protein binding; platelet-derived growth factor binding; protease binding; protein binding; extracellular matrix structural constituent
Biological process: blood vessel development; collagen biosynthetic process; collagen fibril organization; embryonic skeletal system development; positive regulation of canonical Wnt signaling pathway; positive regulation of cell migration; positive regulation of DNA-templated transcription; positive regulation of epithelial to mesenchymal transition; protein localization to nucleus; sensory perception of sound; skeletal system development; skin morphogenesis; tooth mineralization; visual perception; animal organ development; cellular response to acetaldehyde; cellular response to epidermal growth factor stimulus; cellular response to fibroblast growth factor stimulus; cellular response to fluoride; cellular response to glucose stimulus; cellular response to mechanical stimulus; cellular response to retinoic acid; cellular response to transforming growth factor beta stimulus; cellular response to tumor necrosis factor; cellular response to vitamin E; and 15 more
Cellular component: collagen type I trimer; extracellular matrix; extracellular region; endoplasmic reticulum lumen; collagen trimer; cytoplasm; fibrillar collagen trimer; secretory granule
Genetic constraint (gnomAD): Loss-of-function variants: 21 observed, 190.74 expected, observed/expected ratio (o/e) 0.11, 90% interval 0.077 to 0.16. The upper end of that interval is the gene's LOEUF score, 0.16, which puts it in group 1 of 6, group 1 being the genes least tolerant of losing a copy. Missense variants: 1,365 observed, 2,089.5 expected, observed/expected ratio (o/e) 0.65, 90% interval 0.62 to 0.68. Synonymous variants: 749 observed, 767.79 expected, observed/expected ratio (o/e) 0.98, 90% interval 0.92 to 1.04.
Gene-disease validity (ClinGen):
ClinGen rates the evidence that COL1A1 causes each of these diseases.
Caffey disease (autosomal dominant): Definitive. Caffey disease is an osteosclerotic dysplasia characterized by acute inflammation with massive subperiosteal new bone formation usually involving the diaphyses of the long bones, as well as the ribs, mandible, scapulae, and clavicles.
COL1A1-related Ehlers-Danlos syndrome (autosomal dominant): Definitive. Any Ehlers-Danlos syndrome in which the cause of the disease is a variant in the COL1A1 gene.
osteogenesis imperfecta (autosomal dominant): Definitive. Osteogenesis imperfecta (OI) comprises a heterogeneous group of genetic disorders characterized by increased bone fragility, low bone mass, and susceptibility to bone fractures with variable severity.
Homologues: Orthologues: chimpanzee COL1A1 (100% identical), macaque COL1A1 (99% identical), pig COL1A1 (97% identical), dog COL1A1 (95% identical), rat Col1a1 (92% identical), guinea pig COL1A1 (92% identical), mouse Col1a1 (92% identical), tropical clawed frog col1a1 (83% identical), zebrafish col1a1b (73% identical), rabbit COL1A1 (66% identical). Paralogues in human: COL2A1 (72% identical), COL3A1 (62% identical), COL5A2 (60% identical), COL1A2 (60% identical), COL11A1 (44% identical), COL5A1 (44% identical), COL11A2 (42% identical), COL5A3 (40% identical), COL4A5 (38% identical), COL4A1 (38% identical), COL4A2 (36% identical), COL4A4 (35% identical), and 25 more.
Diseases named in the same sentence as COL1A1 in open-access papers:
COL1A1 is named in the same sentence as 488 diseases in open-access papers, as found by Europe PMC text mining. Sharing a sentence is not in itself a finding about the gene and the disease. The quoted sentences say what the papers report.
liver fibrosis (353 papers, 2010 to 2026). "Among the fibrotic markers evaluated, COL1A1 plays a central role in liver fibrosis by encoding a major fibrillar collagen involved in ECM deposition." (PMID 40572736, 2025). "Consistently, elevated serum ALT level reduced significantly after HepG2 EV treatment, which also caused a dramatic attenuation of ACTA2 protein production and reduced expression of liver fibrosis-associated genes including COL1A1 and CCN2." (PMID 40002688, 2025). "Apparently inconsistent associations of COL1A1 peptides has also been reported in the context of liver fibrosis, with most being highly significantly reduced in fibrosis, however, some being increased." (PMID 39740102, 2025). "These dietary attenuations in NAFLD progression were paralleled by lower mRNA expression levels of Col1a1, which encodes for collagen type 1 and is related to developing hepatic fibrosis, than found for HFD-fed mice." (PMID 39599744, 2024). "Both treatments caused liver fibrosis associated with an increased expression of Col1a1 and Acta2 in liver tissue." (PMID 39529885, 2024). "The expression of miR-221/222 is positively correlated with the progression of liver fibrosis and significantly associated with the expression of Col1A1 and αSMA mRNA." (PMID 38476236, 2024). "Hepatic mRNA-expression analysis of Col1a1, which encodes for collagen-type 1—a gene related to the development of hepatic fibrosis —showed that compared to the LFD, HFD-feeding resulted in a trend toward higher expression." (PMID 39599744, 2024). "These genes are known to gradually increase upon NASH progression, with Gdf15 and Ccl20 encoding proinflammatory cytokines, Col1a1 and Col1a2 encoding collagen chain proteins, and Itgbl1 known for regulating liver fibrosis." (PMID 37914694, 2023). "According to IPA, the COL1A1 gene is linked to “fibrosis of the liver”, “cirrhosis of the liver”, “proliferation of hepatic stellate cells”, “diabetes mellitus”, “glucose metabolism disorder”, and “proliferation of liver cells”." (PMID 37511368, 2023). "Increased phosphorylation of p38 was associated with increased COL1A1 mRNA levels, in in vitro systems related to pulmonary veno-occlusive disease and liver fibrosis." (PMID 37373151, 2023). "The aberrant ECM buildup during liver fibrosis is associated with an increase in the half-life of the COL1A1 mRNA from 1.5 h in quiescent HSCs to more than 24 h in active HSCs." (PMID 36435779, 2022). "IL-5 produced by lung-derived ILC2s can drive eosinophilia while IL-13 can stimulate hepatic stellate cells and induce upregulation of fibrosis-associated genes including Col1a1, Acta2 and Timp1, thus promoting liver fibrosis." (PMID 34305911, 2021). "Loss of TNF receptor TNFR1 attenuates liver fibrosis induced by CCl4 or bile duct ligation, accompanied by reduced expression of Col1a1 and Il6 genes and decreased NF-κB activation in liver tissues as well as in isolated HSCs." (PMID 34712238, 2021). "Reduction of hepatic neutrophils and macrophages as well as reduced liver fibrosis was accompanied by a reduction of gene expression levels associated with inflammation (Tnfα, Il10, and Tgfβ) and less pronounced fibrosis (Col1a1, Timp, and Ctgf)." (PMID 32316235, 2020). "In these models, α7nAChR deficiency resulted in exacerbated hepatic fibrosis, higher plasma transaminase levels, and significantly increased Col1a1 gene-encoding alpha-1 type I collagen (mediating liver fibrosis) Ccl2 and Tnf gene expression." (PMID 31024226, 2019). "When compared to the WDB group, the WDO group displayed increased hepatic expression of genes linked to inflammation (Opn, Il1rn, Gdf15), hepatic fibrosis (collagen staining, Col1A1, Thbs2, Lox) reflecting disease progression." (PMID 28422962, 2017). "Chronic feeding the PA-enriched diet caused liver fibrosis as indicated by Sirius red staining and increased Col1A1 mRNA levels, and these effects were magnified in mice fed the combination diet enriched in PA and MA." (PMID 26539645, 2015).
liver fibrosis (continued). "Reduced liver fibrosis in CCL3−/− mice was associated with altered expression of Col1a1, TIMP1, and MMP9 (P<0.05)." (PMID 23799074, 2013). "As a result, elevated TGF-β1 can cause liver fibrosis by increasing the expression rate of COL1A1." (PMID 39290493, 2024). "The liver fibrosis gene, Col1a1, displayed a robust association with K. alysoides and A. muris, suggesting that these bacteria may contribute to liver fibrosis." (PMID 39048678, 2024). "Finally, the analysis of individual transcripts showed that many putative genes associated with liver fibrosis such as Acta2, Col1a1, Lox and Hhipl1 were upregulated in animals fed with SSD." (PMID 37774007, 2023). "Increased level of Col1a1 in Hepatic Stellate Cells causes the presence of hepatic fibrosis." (PMID 32214033, 2020). "However, mRNA levels of genes encoding liver fibrosis markers COL1a1 (RR = 23.5) and TGF-β (RR = 1.41), were higher in mice in the FF-S group than in mice in the NC-S group." (PMID 29179698, 2017). "Therefore, we examined whether TGF-β1 could induce the expression of Col1A1, a gene encoding collagen α1(I) which is predominantly accumulated in the portal region during liver fibrosis." (PMID 23236489, 2012). "Hepatic fibrosis markers (Acta2 and Col1a1) and collagen deposition remained elevated in Tet2ΔMye-CCl4 mice despite IL-1β neutralization." (PMID 41474968, 2026). "In contrast, the expression of liver fibrosis‐related genes (Tgfb1, Col1a1) was significantly increased in the GAN group." (PMID 41559934, 2026). "In TSNO mice, CA markedly enhanced hepatic fibrosis, increased Col1a1 and Timp1 expressions, and promoted CD11c+ monocyte-derived macrophage infiltration." (PMID 41751341, 2026). "By tailoring the probes' specific recognition units to target the COL1A1 mRNA sequence, a biomarker indicative of liver fibrosis." (PMID 40407197, 2025). "Another characteristic of the drug that was improved in the presence of n-3 PUFAs is its ability to prevent hepatic fibrosis as measured through the TGFβ-dependent induction of the COL1A1 gene expression in HepG2 cells." (PMID 40699986, 2025). "Intriguingly, we found that LAPNTG mice are protected from liver fibrosis as reflected by a greatly reduced expression of fibrotic genes such as Col1a1, Col3a1, Col4a4, TGF-β, and SMA." (PMID 39792554, 2025). "Our findings indicated that MCL markedly suppressed COL1A1 and FN expression in liver tissue, suggesting its considerable therapeutic potential for hepatic fibrosis treatment." (PMID 40143066, 2025). "This therapeutic effect was further substantiated by a significant reduction in the protein levels of Col1a1 and fibronectin by using IHC analysis in the HepLPCs-treated rats, highlighting the therapeutic potential of HepLPCs in mitigating liver fibrosis." (PMID 41193418, 2025). "Fibrosis progression in the NASH mouse model was assessed by measuring the relative gene expression levels of liver fibrosis markers, specifically Col1a1 and Acta2, as well as the inflammation marker Mcp1, using RT-qPCR." (PMID 39894410, 2025). "Beyond cancer, LCN2 is associated with fibrosis, where it correlates with COL1A1 expression and drives ECM remodeling in liver fibrosis." (PMID 40472740, 2025). "Activated HSC frequency expressing α-SMA and collagen type I alpha 1 chain (COL1A1) can be monitored to gauge liver fibrosis degree." (PMID 41515160, 2025). "The body reduces liver fibrosis through downregulating the expression of Col1a1 and Col1a2, thereby affecting the PI3K/AKT signaling pathway to induce HSC senescence." (PMID 40243656, 2025). "In our 3D in vitro model, higher type I collagen (COL1A1) content was observed after steatosis induction, recapitulating the human phenotype of liver steatosis leading to liver fibrosis." (PMID 40608687, 2025). "Subsequently, we evaluated hepatic fibrosis by performing immunostaining for anti-collagen type I alpha 1 chain (Col1α1), anti-actin alpha 2 smooth muscle (αSMA), and Sirius red staining." (PMID 39778469, 2025).
liver fibrosis (continued). "TGF-β activates hepatic stellate cells to secrete extracellular matrix protein COL1A1, which in turn induces liver fibrosis." (PMID 39856797, 2025). "Res HDL treatment promoted a significant reduction in liver fibrosis assessed by Sirius Red staining and COL1A1, αSMA staining." (PMID 41320154, 2025). "The excessive synthesis of COL1A1 constitutes a critical driving factor in the development of hepatic fibrosis and liver cirrhosis." (PMID 41306725, 2025). "Wogonoside activated ferroptosis by decreasing the levels of solute carrier family 7 member 11 (SLC7A11), GPX4, and GSH in mouse HSC-T6 cells, while reducing the levels of α-smooth muscle actin (α-SMA) with COL1A1 and alleviating liver fibrosis." (PMID 40278581, 2025). "In human HBV-related liver fibrosis, genes such as COL1A1, TIMP1, ACTA2, and CTGF are consistently upregulated, reflecting structural reorganization and inflammatory signaling cascades." (PMID 41586310, 2025). "This study introduces an in‐situ assembly of fluorogenic RNA approach for screening natural anti‐liver fibrosis compounds and dynamic visualization of endogenous COL1A1 mRNA in live cells." (PMID 40407197, 2025). "Results from LX-2 cells demonstrated that β-sitosterol decreased the protein expression of COL1A1 when compared to the control, indicating its capacity to ameliorate liver fibrosis in both in vivo and in vitro conditions." (PMID 38461449, 2024). "The expression of liver fibrosis-related genes (including Col1a1 and α-SMA) was suppressed following the administration of CS extract." (PMID 39683561, 2024). "The other downregulated gene encodes collagen type I alpha 1 chain (COL1A1), which is the major component of type I collagen, a main constituent of ECM in liver fibrosis." (PMID 39466591, 2024). "We found that increased liver fibrosis in OVX Prmt6 KO mice fed alcohol correlated with elevated mRNA levels of Col1a1, Tgfb1, and Tnf, similarly to WT OVX mice." (PMID 38704651, 2024). "The indication of relevant animal dynamics showed that the longer the administration time of CCl4, the higher contents of liver fibrosis markers Col1A1 and α-smooth muscle actin (α-SMA) in mouse liver tissues." (PMID 38438584, 2024). "While most genes were only up-regulated in one or two groups, collagen I (Col1a1), which is the most abundant collagen in liver fibrosis, was a notable exception, being up-regulated at least 5-fold by TAA in all non-cancer groups." (PMID 39254423, 2024). "This downregulation led to the inhibition of the expression of liver fibrosis proteins α‐SMA and COL1A1, ultimately alleviating liver fibrosis caused by S. japonicum." (PMID 39031798, 2024). "The activation of the TGF-β/SMAD signaling pathway in HSCs resulted in the upregulation of several key genes associated with hepatic fibrosis, including TIMP1, SMAD2, SMAD3, COL1A1, and MMP2, as well as increased secretion of MMP-9 protein." (PMID 39201682, 2024). "Col1A1, Timp1, and Tgfβ1, which are commonly regarded as fibrosis markers, were upregulated in liver fibrosis." (PMID 38372748, 2024). "Knockdown of APTR using adenovirus in CCl4-treated mice resulted in reduced levels of αSMA and COL1A1, and mitigated liver fibrosis." (PMID 39872125, 2024). "These compounds were screened for their inhibitory effects on the COL1A1 promoter to assess in vitro anti-liver fibrosis activity and summarized structure–activity relationships." (PMID 39407703, 2024). "The COL1A1 gene encodes collagen type I alpha I, a major component of ECM deposition in hepatic fibrosis." (PMID 39062514, 2024). "Treatment with α4β7 mAb reduced hepatic fibrosis reflected by decreased collagen deposition in the liver and significant reduction in the transcript levels of Acta2, Col1a1, Col1a2, Tgfb1 and Timp1." (PMID 38727292, 2024).